ZMIZ1 (zinc finger MIZ-type containing 1)
Diseases named in the same sentence as ZMIZ1 in open-access papers (continued):
Sharing a sentence is not in itself a finding about the gene and the disease.
colon cancers (4 papers, 2013 to 2024). "Using in vitro cellular and loss-of-function assays, this study demonstrated that ZMIZ1 plays a critical pro-cancer role in colon cancer and that targeting ZMIZ1 is beneficial in hindering colon cancer progression." (PMID 38214831, 2024). "Several recent population-based cohort studies have indicated that differences in ZMIZ1 expression due to gene mutations or epigenetic regulatory mechanism are significantly associated with the survival of cancer patients, including those with colon cancer." (PMID 38214831, 2024). "The single nucleotide polymorphisms (SNPs) in the ZMIZ1 gene have been identified by several genome-wide association studies (GWAS) to be associated with the risk of prostate cancer, colon cancer and breast cancer." (PMID 38214831, 2024). "Our results are consistent with the trend of previous cohort findings that ZMIZ1 is significantly overexpressed in colon cancer tissues and predicts a poor prognosis for patients." (PMID 38214831, 2024). "Specific shRNA transfection was used to knock down the expression of ZMIZ1 in colon cancer cell lines (HCT116 and HT29), and cell proliferation was detected using EdU and CCK-8 reagents, apoptosis by flow cytometry, and autophagy by western blot." (PMID 38214831, 2024). "All of these studies have demonstrated the critical role of the ZMIZ1 protein in colon cancer and in cancer progression." (PMID 38214831, 2024). "ZMIZ1 is overexpressed in breast and colon cancers, of which patients exhibit reduced survival with high expression levels of ZMIZ1." (PMID 38214831, 2024). "The overexpression of Zmiz1, recently identified as a candidate oncogene, was reported in human breast, ovarian, and colon cancers." (PMID 23847593, 2013). "The aim of this study is to reveal whether ZMIZ1 can control the fate of colon cancer cells and the mechanism by which it functions." (PMID 38214831, 2024). "Targeting ZMIZ1 would be beneficial for the treatment of colon cancer." (PMID 38214831, 2024). "Of interest is the role of ZMIZ1 in autophagy of colon cancer cells." (PMID 38214831, 2024). "The present study is the first of its kind to investigate the knockdown of ZMIZ1 in colon cancer cell lines in vitro using specific shRNA transfection, and found that ZMIZ1 knockdown significantly inhibited proliferation and autophagy and induced apoptosis of cancer cells." (PMID 38214831, 2024). "We hypothesized that ZMIZ1 may control the fate of colon cancer cells through the SIRT1/FOXO3a axis." (PMID 38214831, 2024). "In addition to colon cancer, a few studies have been reported on the molecular function of ZMIZ1 in other types of solid tumors." (PMID 38214831, 2024). "After subsequent rescue experiments, we also demonstrated that ZMIZ1 could promote the malignant proliferation of colon cancer by facilitating the degradation of SIRT1." (PMID 38214831, 2024). "However, to the best of our knowledge, no experiments have been performed to confirm or validate the specific role of ZMIZ1 in colon cancer progression." (PMID 38214831, 2024). "ZMIZ1 may control the fate of colon cancer cells through the SIRT1/FOXO3a axis." (PMID 38214831, 2024). "In conclusion, ZMIZ1 significantly promoted the malignant proliferation of colon cancer cells, possibly by acting as an E3 ubiquitin ligase that regulates the SIRT1/FOXO3a axis, thereby controlling autophagy or apoptosis of colon cancer cells." (PMID 38214831, 2024). "To clarify whether ZMIZ regulates autophagy, proliferation and apoptosis of colon cancer cells through SIRT1, we set up two rescue experiments in which the cells of ZMIZ1 knockdown (ZMIZ-KD) were subjected to SIRT1 knockdown (SIRT-KD) or pharmacological inhibition (SIRT1 Inhibitor) (EX527, 100 nM)." (PMID 38214831, 2024).
Crohn disease (4 papers, 2017 to 2022). A gastrointestinal disorder characterized by chronic inflammation involving all layers of the intestinal wall, noncaseating granulomas affecting the intestinal wall and regional lymph nodes, and transmural fibrosis. "Similarly, we identified a colocalization between a Crohn’s disease locus and a ZMIZ1 eQTL specific to 16 h-stimulated TCM cells." (PMID 35618845, 2022).
developmental delay (4 papers, 2021 to 2025). "Zmiz1-associated neuropsychiatric pathologies due to mutational load as such de novo mutation/missense variant/translocation/chromosomal rearrangements lead to complex behavioral disorders including anxiety, social communication, speech delay, memory recall, ID, and developmental delay." (PMID 38686122, 2024). "We noticed that both OTUD6B- and ZMIZ1-related disorders share nonspecific phenotypes of ID, global developmental delay, hypotonia, microcephaly, feeding difficulty, and distal limb anomalies in at least two-thirds of the patients." (PMID 34680978, 2021).
acute lymphoblastic leukemia (3 papers, 2019 to 2024). Leukemia with an acute onset, characterized by the presence of lymphoblasts in the bone marrow and the peripheral blood. "Even more, ZMIZ1 seems to be related to translocation involving chromosomes 9 and 10 in lymphoblastic leukemia." (PMID 37047552, 2023). "It was reported previously that ZMIZ1, in collaboration with NOTCH1, induce T-cell acute lymphoblastic leukemia (T-ALL) in mice." (PMID 31221986, 2019).
celiac disease (3 papers, 2017 to 2024). An autoimmune genetic disorder with an unknown pattern of inheritance that primarily affects the digestive tract. "This study provides insights into the genetics of celiac disease in the Asian population, and it is the first study from Pakistan reporting the association of the LPP rs1464510 A allele and the ZMIZ1 rs1250552 AG genotype with the risk of celiac disease." (PMID 39062631, 2024). "The current study summarizes that LPP rs1464510 and ZMIZ1 rs1250552 are associated with the risk of celiac disease." (PMID 39062631, 2024). "The current study aimed to check the association of LPP rs1464510 C>A and ZMIZ1 rs1250552 A>G with the risk of celiac disease (CD) in the Pakistani population." (PMID 39062631, 2024). "Statistical analysis revealed that the LPP rs1464510 A allele and the ZMIZ1 rs1250552 AG genotype reduce the risk of celiac disease by 52% and 73%, respectively." (PMID 39062631, 2024). "The association between celiac disease, LPP rs1464510, and ZMIZ1 rs1250552 was further explored and quantified by odds ratio." (PMID 39062631, 2024).
diabetes (3 papers, 2016 to 2024). "In recent years, the importance of Zmiz1 in the pathogenicity of diabetes and cancer has gained significant recognition as well." (PMID 38718095, 2024). "Moreover, research has unveiled previously unknown roles for Zmiz1 in multiple diseases, including leukemia, erythropoiesis, osteosarcoma, diabetes, multiple sclerosis and in a range of neurodevelopmental disorders." (PMID 38718095, 2024).
renal cell carcinoma (3 papers, 2023 to 2024). "The ZMIZ1-related DNAm status is regarded as a molecular marker in multiple cancer types, including astrocytoma, bladder cancer, and renal cell carcinoma." (PMID 37122620, 2023). "In addition, ZMIZ1 is used as a prognostic marker of renal cell cancer, among other types of cancers, rendering it a possible target for anticancer drugs." (PMID 37047552, 2023).
autism (2 papers, 2022 to 2024). Persistent deficits in social interaction and communication and interaction as well as a markedly restricted repertoire of activity and interest as well as repetitive patterns of behavior. "Among these, three (PAX6, TCF4, and ZMIZ1) are ASD risk genes according to the Simons Foundation Autism Research Initiative (SFARI) gene database." (PMID 35942939, 2022). "CPN, particularly affected in Autism, exhibits high Zmiz1 expression during embryonic development, suggesting a potential regulatory role in their generation and maturation." (PMID 38686122, 2024). "Additionally, we compared the DEGs obtained in our RNAseq experiments from Zmiz1-KO cortex at P7 with SFARI Autism gene modules and identified that 16 out of 104 DEGs uniquely map to SFARI Autism risk genes." (PMID 38686122, 2024). "ZMIZ1 mRNA is a target of Fragile X Mental Retardation Protein (FMRP), a well-studied protein in autism." (PMID 38686122, 2024).
autism spectrum disorder (2 papers, 2024 to 2025). A spectrum of developmental disorders that includes autism, and Asperger syndrome. "Recent case studies have also revealed Zmiz1 variants as a cause for various syndromic neurodevelopmental disorders and risk factors for autism spectrum disorder." (PMID 38718095, 2024).
Autoimmunity (2 papers, 2024). The occurrence of an immune reaction against the organism's own cells or tissues. "GWAS studies in MS patients identified downregulation of Zmiz1 in autoimmunity and as an MS risk gene." (PMID 38686122, 2024). "Recently, ZMIZ1 was identified as being significantly upregulated in a transcriptome-wide association study of AITD, increasing its appeal for further research in AITD and its role in autoimmunity." (PMID 37962983, 2024).
colorectal cancer (2 papers, 2017 to 2022). A primary or metastatic malignant neoplasm that affects the colon or rectum. "Multiple studies reported that rs704017, located in the intron of the ZMIZ1 gene, is the genetic risk factor associated with colorectal cancers (CRC)." (PMID 35372566, 2022).
depression (2 papers, 2022 to 2024). "Analysis of differentially expressed genes in the dentate gyrus of a depression mouse model indicates that Zmiz1 potentially functions in regulating key upregulated hub genes, linking it to the pathogenesis of depression." (PMID 38686122, 2024).
endometrial cancer (2 papers, 2025). Primary or metastatic malignant neoplasm involving the endometrium (mucous membrane that lines the endometrial cavity). "ZMIZ1 mutations are found in endometrial cancer and its RNA levels trend toward reduction in endometrium of patients with endometriosis." (PMID 41321316, 2025). "ZMIZ1 deficiency was associated with endometriosis and endometrial cancer, and conditional ablation of Zmiz1 using the PgrCre mouse led to infertility and accelerated fibrosis due to impaired estrogen responsiveness." (PMID 41321319, 2025). "Dysregulation of ESR1 cofactors, exemplified by ZMIZ1, may underline a spectrum of estrogen-dependent conditions, including endometriosis, endometrial cancer, and other hormone-driven disorders." (PMID 41321319, 2025). "Expression of ZMIZ1 RNA and protein in multiple uterine cell types and the analysis of clinical datasets showing ZMIZ1 mutations in endometrial cancer and the potential impact of ZMIZ1 expression levels on endometrial cancer and endometriosis underlines its possible importance in uterine function." (PMID 41321316, 2025). "Here, we investigate the role of ZMIZ1 in human endometrial stromal cells and the mouse uterus, as well as potential impacts on endometrial cancer and endometriosis, using human and mouse models." (PMID 41321316, 2025). "Alterations in ZMIZ1 are detected in up to 14% of endometrial cancers." (PMID 41321319, 2025). "Whether ZMIZ1 exerts similar transcriptional regulatory roles in endometrial cancer remains an important question, particularly with respect to its influence on ESR1-driven gene programs." (PMID 41321319, 2025). "ZMIZ1 disruption inhibited estrogen-dependent growth of Ishikawa cells, which are derived from endometrial cancer, suggesting development of ZMIZ1-targeting might be therapeutic." (PMID 41321316, 2025).
endometriosis (2 papers, 2025). The growth of functional endometrial tissue in anatomic sites outside the uterine body. "Their findings extend the current paradigm of steroid hormone action by demonstrating how loss of ZMIZ1 disrupts these intersecting pathways, resulting in impaired decidualization, infertility, fibrotic remodeling, and phenotypes reminiscent of endometriosis." (PMID 41321319, 2025). "IHC analysis of samples from eutopic endometria and lesions from endometriosis patients indicated ZMIZ1 protein was detected but varied substantially between individual patients." (PMID 41321316, 2025). "In women with endometriosis, reduced ZMIZ1 expression in the eutopic endometrium parallels impaired stromal PGR activity, supporting its role in attenuated progesterone signaling and the development of progesterone resistance." (PMID 41321319, 2025). "These ZMIZ1 activities could initiate endometrial pathologies, including uterine cancer, endometriosis, or fibroids." (PMID 41321316, 2025). "Indeed, a previous study identified ZMIZ1 as one of multiple genes upregulated in ectopic versus eutopic endometrium of women with endometriosis." (PMID 41321316, 2025). "Moreover, ZMIZ1’s established functions in immune regulation suggest additional relevance in the pathophysiology of primary dysmenorrhea, a frequent comorbidity of endometriosis, where immune dysregulation contributes to chronic pelvic pain and lesion progression." (PMID 41321319, 2025). "Additionally, analysis of ZMIZ1 expression in endometrial samples in the Turku Endometriosis Bulk RNA-seq Database suggests a nonsignificant decrease in ZMIZ1 levels at the proliferative phase in patients with endometriosis compared with normal samples." (PMID 41321316, 2025).
hearing loss (2 papers, 2023 to 2025). "Normothermia TTM upregulated 13 genes associated with hearing loss, including Loxhd1, Tecta, Zmiz1, Espn, Gjb2, Sesn3, Bdp1, Hg, Pax3, Rnls, Syne4, P2rx2, and Pou3f4." (PMID 38298897, 2023). "Phenotypes observed in patients with ZMIZ1 mutations, such as hearing loss, cognitive and learning disability, and sleep alterations, may be related to dysregulation of CTN functions." (PMID 40529245, 2025).
hepatocellular carcinoma (2 papers, 2024 to 2025). A malignant tumor that arises from hepatocytes. "Another study uncovered the critical role of TET3-mediated DNA hydroxymethylation of ZMIZ1, a mechanism that activates the Notch1/c-Myc axis, alters macrophage polarization status, and ultimately affects hepatocellular carcinoma progression." (PMID 41299461, 2025). "ZMIZ1 collaborates with Notch1 to activate c-Myc transcription and promotes M2 polarization in Kupffer cells, thereby enhancing hepatocellular carcinoma transformation." (PMID 38866828, 2024). "However, knockdown of ZMIZ1 in Kupffer cells inhibited M2 polarization, which consequently restrained hepatocellular carcinoma progression." (PMID 38866828, 2024).
infertile (2 papers, 2025). "Consequently, altered ZMIZ1 expression or activity could serve as a molecular marker of endometrial receptivity, offering potential diagnostic and therapeutic value in infertility management." (PMID 41321319, 2025). "Ablation of Zmiz1 using the PgrCre mouse (Zmiz1d/d) resulted in infertility and accelerated age-dependent uterine fibrosis." (PMID 41321316, 2025). "The infertility may have a contribution from Zmiz1 deletion in the pituitary and ovary, resulting in disruption on the neuroendocrine control of pregnancy in the mouse." (PMID 41321316, 2025).
microcephaly (2 papers, 2021 to 2025). A congenital or acquired developmental disorder in which the circumference of the head is smaller than normal for the person's age and sex. "It was recently reported that mutations in ZMIZ1 can cause a rare neurodevelopmental syndrome characterized by growth failure, feeding difficulties, microcephaly, facial dysmorphism, and various other congenital malformations." (PMID 39948187, 2025).
osteosarcoma (2 papers, 2024 to 2025). A usually aggressive malignant bone-forming mesenchymal neoplasm, predominantly affecting adolescents and young adults. "Overall, these findings showed that loss of Zmiz1 negatively affects LEC proliferation and migration and are consistent with previous Zmiz1 studies in T-cells, melanocytes and osteosarcoma." (PMID 38718095, 2024).
psoriasis (2 papers, 2017 to 2022). An autoimmune condition characterized by red, well-delineated plaques with silvery scales that are usually on the extensor surfaces and scalp. "More than 4500 cases and 10,000 controls were investigated in GWAS, where 7 non-HLA susceptibility loci shared by CD and psoriasis (9p24 near JAK2, 10q22 at ZMIZ1, 11q13 near PRDX5, 16p13 near SOCS1, 19p13 near FUT2, 17q21 at STAT3, 22q11 at YDJC) were found." (PMID 36443384, 2022).
skin tumors (2 papers, 2014 to 2021). "Insertions into Zmiz1 and Mamld1 have been previously observed in skin tumors induced by transposon insertional mutagenesis." (PMID 34398873, 2021). "Recently we described skin tumors driven by skin-specific expression of Zmiz1 and here we define keratoacanthoma pathobiology in this mouse model." (PMID 25309748, 2014).
tongue squamous cell carcinoma (2 papers, 2024 to 2025). A squamous cell carcinoma that arises from the tongue. "Among these genes, GDF15 has been confirmed to play a metastasis‐promoting role in most studies, whereas ZMIZ1 has been found to affect invasion and metastasis in tongue squamous cell carcinoma (TSCC)." (PMID 39817582, 2025). "The function of ZMIZ1 in tongue squamous cell carcinoma (TSCC) and the mechanisms underpinning its role in this disease have not been fully clarified." (PMID 38866828, 2024).
adrenal carcinoma (1 paper, 2011). A carcinoma involving a adrenal gland. "Next, we further assessed the role of the SWI/SNF-mediated complexes in ZMIZ1 regulated AR activity using the human adrenal carcinoma cell line, SW13, which is deficient in both BRG1 and Brm expression and considered to lack functional SWI/SNF complexes." (PMID 21949845, 2011).
breast tumours (1 paper, 2024). "To explore if the role of ZMIZ1 activity held clinical importance, we investigated if ZMIZ1 expression was a predictor of patient survival in the context of both ER-positive and ER-negative breast tumours using KMplot." (PMID 38564418, 2024).
cholangiocarcinoma (1 paper, 2024). A carcinoma that arises from the intrahepatic biliary tree (intrahepatic cholangiocarcinoma) or from the junction, or adjacent to the junction, of the right and left hepatic ducts (hilar cholangiocarcinoma). "report that hepatocyte-specific ZMIZ1 knockout mice exhibit significant hindrance of intrahepatic cholangiocarcinoma formation." (PMID 38214831, 2024).
coronary artery disease (1 paper, 2022). "Here, we detected ZMIZ1, which plays a crucial role in vasculogenesis and heart morphogenesis and may contain super‐enhancer SNPs that are associated with coronary artery disease." (PMID 36540645, 2022).
endometrial tumor (1 paper, 2025). "To assess a potential role for ZMIZ1 in endometrial epithelial cells, we evaluated the impact of ZMIZ1 in Ishikawa cells, an epithelial cell line derived from an endometrial tumor." (PMID 41321316, 2025).
neuroblastoma (1 paper, 2025). Neuroblastoma (NB) is the most common solid, extracranial childhood tumor. "ZMIZ1 is a coactivator of the androgen receptor (AR), which has been shown to regulate transcriptional activity of the μ-opioid receptor in both rats and human neuroblastoma cell lines." (PMID 40937335, 2025).
nicotine dependence (1 paper, 2025). Physical and psychological dependence on nicotine. "Lower ZMIZ1 DNAm levels have been shown to be associated with smoking status but not with nicotine dependence, although this CpG site (cg18688392), also identified by another EWAS on smoking, was not located in the current CMR." (PMID 40937335, 2025).
non-melanoma skin carcinoma (1 paper, 2019). "ZMIZ1 is also a candidate oncogene in non-melanoma skin cancer." (PMID 31221986, 2019).
Obesity (1 paper, 2022). Accumulation of substantial excess body fat.